CELSR2 (cadherin EGF LAG seven-pass G-type receptor 2)
Diseases named in the same sentence as CELSR2 in open-access papers (continued):
Sharing a sentence is not in itself a finding about the gene and the disease.
cardiovascular diseases (2 papers, 2023 to 2025). "We also identified the protective effect of CELSR2 on cardiovascular diseases (CAD, MI, HF, CHD), suggesting its potential as a therapeutic target for CAS." (PMID 40649979, 2025). "A cluster of three genes CELSR2, PSRC1, and SORT1 has been associated with cardiovascular diseases." (PMID 36975855, 2023).
CELSR2 also shares sentences with these, for which no sentence is quoted: lymphoma (2 papers); Alzheimer disease (1); aortic stenosis (1); Ataxia (1); carotid atherosclerosis (1); congenital heart defects (1); dementia (1); hyperlipidemia (1); leukemia (1); male infertility (1); neural tube defect (1); neurological diseases (1); pulmonary stenosis (1); spina bifida (1).